ACKR2 (atypical chemokine receptor 2)
Diseases named in the same sentence as ACKR2 in open-access papers (continued):
Sharing a sentence is not in itself a finding about the gene and the disease.
tumor (continued). "However, it has been recently demonstrated that ACKR2 also hinders tumor infiltration of NK cells by limiting their expression of CCR2, finally supporting metastasis." (PMID 30591657, 2018). "Collectively, these results suggest that neutrophil activation during tumor progression is constrained by ACKR2, which impinges on their expression of CC chemokine receptors and inhibits their migration to the lung and their ability to generate ROS, key mediators of neutrophil antitumoral potential." (PMID 29445158, 2018). "We followed primary tumor development measuring time of appearance and volume, and found that in NeuT/Ackr2−/− mice tumor masses in mammary glands developed earlier and reached higher volumes as compared to NeuT/Ackr2+/+ mice." (PMID 29445158, 2018). "Restoration of D6/ACKR2 expression in ATC cells could be a novel strategy to block ATC progression by dampening inflammation in tumor microenvironment given the ability of D6/ACKR2 to scavenge chemokines so as to decrease leukocyte infiltration." (PMID 28740576, 2017). "In this context, although an inverse correlation between ACKR2 expression and tumor stage was observed, it is unclear whether this correlation can be utilized as a clinical prognostic marker." (PMID 28123388, 2016). "As a chemokine scavenger, ACKR2 may suppress immune cell infiltration by sequestering pro‐inflammatory chemokines, which could contribute to the development of immune‐excluded tumour niches." (PMID 40318012, 2025). "Therefore, analyzing vascular tumors in terms of ACKR2 expression to find the origin of the tumor might be promising in detecting the type of cancer." (PMID 35677043, 2022). "Importantly, ACKR2 plays diverse and complex roles in tumour biology from initiation to metastasis." (PMID 33801414, 2021). "However, in this context of non-conventional cancer-related chemokine activities, it is possible that ACKR2 may also have pro-tumor effects." (PMID 32582148, 2020). "The interaction between ACKR2 and CCL13, CCL7 illustrates that SLC40A1+ TAMs and APOC1+ TAMs be recruited by ECs to modulate tumor immunity." (PMID 39232806, 2024). "Lungtumor-outgoing ligand CCL connected to the tumor and AN as incoming signals via the receptors CCR1 and ACKR2/4, respectively." (PMID 37106167, 2023). "These chemokines also interact with the atypical chemokine receptors (ACKR2, ACKR3, ACKR4) expressed by both keratinocytes and fibroblasts, provoking excessive Th17 responses and amplifying skin inflammation." (PMID 37308489, 2023). "The expression of ACKR2 and ACKR4 in the tumor was, respectively, 3.1-fold and 1.5-fold lower than in patient-matched macroscopically normal tissue." (PMID 33374792, 2020). "The active form of CCL14 can also be broken down by atypical chemokine receptor 2 (ACKR2)/D6; however, the expression of this receptor decreases as the tumor develops." (PMID 33182504, 2020). "Patients with high expression of atypical chemokine receptor 2 (ACKR2) may bind and internalize CCL2 for intracellular degradation to limit tumor metastasis, thus leading to low recruitment of CCR2+ monocytes along with high recruitment of CCR2+ NK cells." (PMID 36880535, 2023). "Indeed, these newly identified chemokines for ACKR2 and GPR182 are key players in driving NK cells and CD8+ T cells into the tumor bed." (PMID 37153591, 2023). "Resembling ACKR1 and many of the functions of ACKR2, ACKR4 demonstrates predominantly tumor-restricting effects, and was positively correlated with patient survival rates in several cancers; at times, ACKR4 expression was inversely correlated with the expression of chemokines in patient materials." (PMID 32582148, 2020). "On the contrary, the lack of ACKR2 resulted in accumulation of CC chemokines and infiltration of leukocytes at tumor sites." (PMID 32456359, 2020). "Beyond ACKR1, the atypical receptor ACKR2, previously called D6, has been detected in tumor specimens, where it plays a negative role in tumor growth and metastasis." (PMID 30591657, 2018).
tumor (continued). "Transfer of Ackr2−/−, but not WT, neutrophils into WT tumor-bearing mice significantly reduced the metastatic ratio to values comparable to those observed in Ackr2−/− tumor-bearing mice." (PMID 29445158, 2018). "In NSG mice, Ackr2 targeting did not affect tumor growth or weight." (PMID 40248897, 2025). "The clinical relevance of these biomarkers has been extensively validated: CXCL14 expression in tumor stroma has been confirmed as an independent survival marker, with fibroblast-derived CXCL14 promoting epithelial-to-mesenchymal transition and metastasis through ACKR2-dependent mechanisms." (PMID 41139924, 2025). "At 25 weeks of age, NeuT/Ackr2−/− mice presented a further significant increase of blood monocytes and neutrophils compared to Ackr2−/− and NeuT/Ackr2+/+, indicating that the lack of ACKR2 was a further driver of tumor-induced myelopoiesis and/or BM release of myeloid cells." (PMID 29445158, 2018). "As depletion and adoptive transfer experiments clearly pointed to neutrophils as the key elements responsible for protection against metastasis observed in the absence of ACKR2, we evaluated their reactive oxygen species (ROS) production, one of the main mechanism of tumor cell-killing." (PMID 29445158, 2018). "In this latter tumor, we have found that ACKR2 expression is downregulated in more aggressive tumors by the activation of the KRAS/BRAF/ERK pathway, thus unleashing chemokine-mediated macrophage recruitment and their acquisition of an M2-like phenotype that sustains angiogenesis and tumor growth." (PMID 28123388, 2016). "In addition, ACKR2 expression was correlated to the expression of its counterpart ligand, i.e., CCL2, but not CCL5 and CCL8, suggesting that ACKR2 downregulation increases CCL2 in the tumor microenvironment to recruit more inflammatory cells and promote inflammation." (PMID 35677043, 2022). "In this study ACKR2 was predominately expressed in LECs of human oral squamous cell carcinomas (OSCC) and not tumor cells or epithelial cells, and the levels in tumor LECs were upregulated compared to normal LECs." (PMID 31105685, 2019). "Nonetheless, this anti-inflammatory activity of ACKR2 not always is beneficial, because this receptor may also lead to a reduced CCR2 expression by NK cells and limiting their infiltration of tumor tissue, what finally supports metastasis." (PMID 32456359, 2020).
cancer (20 papers, 2013 to 2025). A tumor composed of atypical neoplastic, often pleomorphic cells that invade other tissues. "The abnormal expression of ACKR2 is associated with many human diseases, including hepatitis, psoriasis, and cancer 15-17." (PMID 37056937, 2023). "This balanced approach is essential to harnessing ACKR2 as a valuable target in next-generation cancer immunotherapies." (PMID 40248897, 2025). "By integrating pan-cancer data from TCGA, TARGET, and GTEx, the expression patterns of Atypical Chemokine Receptor 2 (ACKR2) across 34 cancers and its correlation with Overall Survival (OS) and Progression-Free Interval (PFI) were analyzed." (PMID 41315216, 2025). "In human cancer lesions, ACKR2 was found to be expressed by peritumoral LVs in oral squamous cell carcinomas and in colon cancer." (PMID 28123388, 2016). "Accordingly, murine models of inflammation-induced cancer in the skin and in the gut revealed that ACKR2 protects mice from the development of tumors by dampening inflammation." (PMID 28123388, 2016). "Several studies using ACKR2-deficient mice or human samples have demonstrated an important role of ACKR2 expressed by LVs in inflammatory conditions and in cancer." (PMID 28123388, 2016). "These contrasting roles underscore the complexity of chemokine regulation within the TME and suggest that while ACKR2 could serve as a potential therapeutic target, its modulation must be carefully tailored to the specific cancer context." (PMID 40248897, 2025). "The elimination of ACKR2 decreases the migration of CXCL14-induced cancer cells." (PMID 37056937, 2023). "In particular, ACKR2 knockdown abolished CXCL14-induced cancer cell motility." (PMID 37056937, 2023). "In cancer, ACKR2 has been shown to act as a double-edged sword and play a paradoxical role." (PMID 35677043, 2022). "However, it was demonstrated that expression of ACKR2 can regulate the micro-environment in some malignant tumors, suggesting a possible role of these receptors in carcinogenesis." (PMID 32456359, 2020). "The individual analysis of expression level in normal and pathological mucosa showed stable expression in macroscopically normal tissue and an insignificant drop at score three with the subsequent significant gradual increase in ACKR2 expression through increasing stages of cancer advancement." (PMID 33374792, 2020). "Targeting hematopoietic ACKR2 may pave the way to innovative therapeutic strategies unleashing myeloid cell-mediated protection against infection and cancer." (PMID 29445158, 2018). "Another challenging issue yet to be resolved is to understand whether ACKR2 could be a putative target for cancer immunotherapy." (PMID 28123388, 2016). "Thus, understanding the molecular mechanisms supporting the scavenger activity of ACKR2 may pave the way to innovative therapeutic strategies against inflammation and cancer." (PMID 32957704, 2020). "ACKR2 in hematopoietic precursors thus operates as a checkpoint for myeloid cell mobilization and effector functions, and its targeting may pave the way to innovative therapeutic strategies, unleashing myeloid cell-mediated protection against cancer." (PMID 29445158, 2018). "Indeed, it remains to be investigated if the activity of ACKR2 on lymphatics promotes or inhibits adaptive immune responses and whether ACKR2, by shaping chemokine gradients, can influence cancer cell dissemination to metastatic organs." (PMID 28123388, 2016). "CXCR7, a member of the subgroup of atypical chemokine receptors (ACKRs) known also as ACKR3, opens the gate for discussion of atypical activities of additional ACKRs in cancer: ACKR1 (DARC, Duffy), ACKR2 (D6), and ACKR4 (CCRL1)." (PMID 32582148, 2020). "Thus, to broaden the scope of atypical activities of chemokine receptors in cancer, a section of the review is dedicated to atypical roles of additional members of the ACKRs sub-group in malignancy: ACKR1, ACKR2, and ACKR4." (PMID 32582148, 2020).
cancer (continued). "In patients with polyps, ACKR2 markedly correlated solely with CCL3, which was also the strongest correlation in CRC patients, although in cancer the significant correlations were present between the receptor and all examined chemokines from MIP and MCP family." (PMID 33374792, 2020). "Since 4T1 cells expressed little or no Ackr2, before and after in vivo growth, these results suggested that the regulatory function of ACKR2 on metastasis is not cancer cell-intrinsic." (PMID 29445158, 2018). "The involvement of ACKR2 in CXCL14-triggered signaling pathways, such as phospholipase Cβ3, protein kinase Cα, and proto-oncogene tyrosine-protein kinase Src, which subsequently upregulate nuclear factor kappa B transcriptional activity, leads to cancer cell EMT and migration." (PMID 40786043, 2025). "However, the precise role of ACKR2 in cancer is not fully elucidated yet." (PMID 32456359, 2020).
infection (6 papers, 2015 to 2022). The state of being infected such as from the introduction of a foreign agent such as serum, vaccine, antigenic substance or organism. "In addition, lack of ACKR2 did not worsen HSK after infection with 6.0 x 106 pfu of HSV-1 virus which was close to maximal levels in WT mice, and less but still severe in ACKR2-/- mice." (PMID 36518752, 2022).
adenocarcinoma (3 papers, 2020 to 2023). A common cancer characterized by the presence of malignant glandular cells. "In adenocarcinomas, the expression ratios (normal-to-pathological) of ACKR2 were positively correlated with all those chemokines while in polyps, with CCL3 and less markedly with CCL4 and CCL7." (PMID 33374792, 2020). "In turn, the actual adenocarcinomas had less pronounced ACKR2 downregulation." (PMID 33374792, 2020).
renal disease (1 paper, 2024). "The atypical chemokine receptor 2 (ACKR2) is a chemokine scavenger receptor, which limits inflammation and organ damage in several experimental disease models including kidney diseases." (PMID 38799420, 2024).
ACKR2 also shares sentences with these, for which no sentence is quoted: colon cancer (3 papers); glioma (3); non-small cell lung carcinoma (2); albuminuria (1); Alzheimer disease (1); atherosclerosis (1); bacterial pneumonia (1); brain trauma (1); brain tumor (1); chronic obstructive pulmonary disease (1); depression (1); fibrosarcoma (1); gastric cancer (1); inflammation (1); intestinal tumors (1); kidney inflammation (1); Lewis lung carcinoma (1); ovarian cancer (1); papillary thyroid carcinomas (1); precocious puberty (1); Splenomegaly (1); systemic sclerosis (1); vascular tumor (1); villous adenoma (1); viral infection (1).